FGFR3 (fibroblast growth factor receptor 3)
Diseases named in the same sentence as FGFR3 in open-access papers (continued):
Sharing a sentence is not in itself a finding about the gene and the disease.
bladder cancer (continued). "Techniques for detecting bladder cancer based on urine DNA or RNA, such as the detection of mutations and methylation of telomerase reverse transcriptase (TERT), Fibroblast growth factor receptor 3 (FGFR3), Vimentin (VIM), and One Cut Homeobox 2 (ONECUT2) genes, have become the focus of research." (PMID 41281744, 2025). "Additionally, the inhibition of FGFR3 has been shown to upregulate MHC class I expression in bladder cancer, implying that FGFR3 downregulates this expression normally." (PMID 40227644, 2025). "In bladder cancer, the MAPK pathway is highly associated with FGFR3 mutations, commonly observed in low-grade bladder cancer but also present in some patients with high-grade invasive bladder cancer, thereby enhancing the tumor’s invasiveness and metastatic potential." (PMID 39911393, 2025). "We focused on assessing the functional role of FGFR3 in the growth of bladder cancer cells." (PMID 41228379, 2025). "Patients with FGFR3-mutant bladder cancer exhibit greater sensitivity to FGFR inhibitor therapy." (PMID 41438986, 2025). "Mutations in PIK3CA, FGFR3, and ERBB2 highlight the relevance of the receptor tyrosine kinase (RTK)–RAS–PI3K signaling cascade in urothelial cancer pathogenesis, in line with previous studies documenting PI3K pathway alterations in 20–30% of bladder cancers." (PMID 41373802, 2025). "FGFR3 was found more frequently in bladder cancer and is thought to be involved in tumor growth." (PMID 41228379, 2025). "We identified prominent negative associations of FGFR3 mutations (especially p.S249, p.Y375) with 11 immune and three stromal cell types in bladder cancer, suggesting FGFR3 may have a role in establishing an immunosuppressive TME in bladder cancer." (PMID 40615649, 2025). "Therefore, FGFR3 serves as a therapeutic target for bladder cancer immunotherapy and also as a predictive marker for diagnosing BC." (PMID 39559360, 2024). "NEDD4 could be a key E3 ubiquitin ligase that regulates PD-L1 for destruction in FGFR3-driven bladder cancer." (PMID 38638430, 2024). "One retrospective study of 72 patients with bladder cancer reported the presence of FGFR3 mutations in 64% of pTa bladder cancers and none in higher stage tumors." (PMID 38675715, 2024). "In the bladder cancer, the FGFR3 is considered as an actionable target." (PMID 38635549, 2024). "In bladder cancer cell lines, it has been shown that FGFR3 expression is induced by hypoxia." (PMID 39031286, 2024). "It will be crucial to investigate MYC alterations in FGFR3 aberrant urothelial bladder cancer, as it may provide further insight into the pathogenesis of bladder cancer, and it could also have therapeutic implications." (PMID 39031286, 2024). "Previous works have examined the role of FGFR3 mutations in murine models of bladder cancer and, with the exception of a recent report, have consistently demonstrated that FGFR3 mutations alone are not sufficient to promote urothelial tumorigenesis." (PMID 38226620, 2024). "MYC is a key downstream effector of activated FGFR3 that mediates tumorigenesis in bladder cancer." (PMID 39031286, 2024). "On this basis, the combination of FGFR3, TERT, and HRAS proto-oncogene mutations resulted in a sensitivity of 93% and a specificity of 89% for the diagnosis of bladder cancer, which shows that the combination of DNA methylation testing has great potential in the detection of bladder cancer." (PMID 39766341, 2024).
bladder cancer (continued). "Two others, NUCB1 [OR: 5.65, 95% CI: 2.64 to 12.09; PP4: 0.98] and FGFR3 [OR: 2.54, 95% CI: 1.77 to 3.66; PP4: 0.99] were both associated with a higher risk of bladder cancer and were observed to have associations with other cancers, including luminal B breast cancer and lung adenocarcinoma." (PMID 38684708, 2024). "Although FGFR3 mutations are relatively common in low-grade bladder cancer, not all patients with urothelial carcinoma exhibit FGFR3 mutations." (PMID 39664176, 2024). "Stabilization of HIF-1α increases FGFR3 mRNA and protein levels in bladder cancer." (PMID 38542288, 2024). "Studies have shown that the antitumor effects of FGFR inhibition in FGFR3 dependent bladder cancer cells and other FGFR dependent cancers may be mediated through c-MYC, a key downstream effector of activated FGFR that is involved tumorigenesis." (PMID 39031286, 2024). "This work provided a molecular clue among NEDD4, PD-L1 and FGFR3, suggesting that targeted therapy in combination with immune therapy could be much better for the treatment of bladder cancer." (PMID 37215134, 2023). "FGFR3 is a biomarker of immune infiltration and immunotherapy response of bladder cancer." (PMID 37251404, 2023). "FGFR3 and TERT are the most frequently mutated oncogenes for bladder cancer." (PMID 38994482, 2023). "It is plausible that the downregulation of FGFR3 by quisinostat we observed in this study may be either an FGFR isoform specific (FGFR3 vs. FGFR2) or a cancer type specific (bladder cancer vs. cholangiocarcinoma) effect." (PMID 37479885, 2023). "Studies have shown that FGFR 2 and FGFR 3 play an important role in bladder cancer." (PMID 37370148, 2023). "In this study, we discovered the potential FGFR3 inhibitors as anti-bladder cancer agents." (PMID 36765337, 2023). "FGFR3 was observed to efficiently detect bladder cancer in patients with low grade tumors whereas NMP-22 (unspecified test platform) and BTAstat were shown to outperform cytology in detecting G3 tumors, with the former also showing significantly higher detection rates for G1 and G2 tumors." (PMID 36765672, 2023). "Interestingly, of the different receptor subtypes FGFR3 is the most involved in the progression of bladder cancer." (PMID 37048074, 2023). "FGFR3 disrupts PD-L1 via NEDD4 to control T cell-mediated immune surveillance of bladder cancer." (PMID 37880682, 2023). "We describe two patients with programmed death ligand-1 (PD-L1)-negative advanced bladder cancer, one with FGFR3 mutation and another with FGFR3 wild type." (PMID 37124509, 2023). "Similarly, abnormal amplifications of the ERBB2, mdm2 and FGFR3 genes were found at a high frequency in bladder cancer." (PMID 38067407, 2023). "The approval of FGFR-TKI followed the recent evidence that alterations in the fibroblast growth factor receptor 3 (FGFR3) gene are common in non-invasive bladder cancer and can be used to identify patients who may benefit from targeted therapy." (PMID 37425564, 2023). "Note that germline SNPs in both FGFR3 and TERT have been associated with bladder cancer risk." (PMID 38994482, 2023). "FGFR3 destabilized PD-L1 via NEDD4 to govern T-cell-involved immune surveillance in bladder cancer." (PMID 36733484, 2023). "Activating point mutations are found in FGFR2 in endometrial cancer and in FGFR3 in bladder cancer." (PMID 36385700, 2023). "FGFR3 is an eligible target for the treatment of bladder cancer." (PMID 37497216, 2023). "From previous studies, FGFR3 is a prognosis marker and could affect the immunotherapy response rate of bladder cancer." (PMID 35615381, 2022). "In the search query, we entered “bladder cancer detection” OR “urothelial cell carcinoma” AND “biomarkers” OR “molecular marker test” OR “UroVysion” OR “NMP22” OR “Fibroblast Growth Factor Receptor (FGFR) 3”." (PMID 36359539, 2022).
bladder cancer (continued). "We generated organoids from two upper tract urothelial carcinomas and from one bladder cancer sample, and confirmed the expression of cytokeratins as urothelial antigens, vimentin as a mesenchymal marker, and fibroblast growth factor receptor 3 by immunohistochemistry." (PMID 35682984, 2022). "In bladder cancer, genomic alterations were most common in FGFR3, particularly in the form of SVs." (PMID 36462464, 2022). "However, studies in models of FGFR3-fusion harbouring bladder cancer lines have so far been limited to a single cell line, RT-112, which harbours a FGFR3-TACC3 fusion as well as an amplification." (PMID 35501832, 2022). "Anti-FGFR3 activation mutation therapy is approved for the treatment of bladder cancer carrying FGFR3 activation mutation, but we did not observe activation mutation of FGFR3 in these specimens." (PMID 36612265, 2022). "Our findings demonstrate that resistance can be overcome by combination treatment with a pan-ERBB inhibitor and suggest that upfront combination treatment with FGFR and pan-ERBB inhibitors warrants further investigation for FGFR3-fusion harbouring bladder cancers." (PMID 35501832, 2022). "The previous study reported mutations in the receptor FGFR3 and protein PIK3CA in bladder cancer." (PMID 36430344, 2022). "FGFR3 amplification is the most common FGFR amplification event in urothelial/bladder cancer." (PMID 34068954, 2021). "According to KEGG Pathways, miR-23 up-regulates MAPK1 and FGFR3 genes in bladder cancer." (PMID 34198846, 2021). "A study on bladder cancer found that the FGFR3 gene is related to cell adhesion." (PMID 34178679, 2021). "Alteration in FGFR3 is responsible for progression of bladder cancer, but this gene might be important for development of pituitary prolactinoma." (PMID 33709028, 2021). "In bladder cancer, daidzein exerts antitumor activity via inhibition of the FGFR3 pathway." (PMID 34540371, 2021). "Mutation status of APC, SPTAN1, and FGFR3 and the level of mutational contribution from APOBEC-related signatures were identified as potential predictive biomarkers for chemoresection with mitomycin C in non–muscle-invasive bladder cancer patients." (PMID 34934968, 2021). "FGFR3 mutations that lead to constitutive activation of downstream signaling pathways in the absence of FGF are commonly found in bladder cancers." (PMID 34984415, 2021). "More than 70% of newly diagnosed bladder cancers belong to NMIBC, which is characterized morphologically by frequent papillary structures, and genetically by deletion of chromosome 9 and point mutation of fibroblast growth factor receptor 3 (FGFR3)." (PMID 34257543, 2021). "Also, gain-of-function mutations in FGFR3, as well as activation of PPAR-γ pathway, have been associated with the T cell exclusion in tumor microenvironment in bladder cancer." (PMID 33874915, 2021). "Additionally, FGFR3 mutations are associated with lower PD-L1 expression, a marker that has been shown to have some correlation with ICI response in some bladder cancer trials." (PMID 33224141, 2020). "Wnt/β-catenin signaling, which is associated with non-T-cell-inflamed tumors both in bladder cancers and across most solid cancers, has been shown to overlap with FGFR3 signaling." (PMID 33224141, 2020). "Tracing FGFR3 mutation is currently used for following bladder cancer recurrence but no related therapeutic options became available." (PMID 32111026, 2020).
bladder cancer (continued). "Overall, the most frequently mutated drug target genes were BRAF for thyroid cancer, FGFR2 for endometrial cancer, EGFR for brain tumors, MGMT for colorectal cancer, FGFR2 and FGFR3 for bladder cancer, NTRK3 for non-small cell lung cancer and NTRK2, FGFR2, EGFR for stomach cancer." (PMID 32111026, 2020). "The FGFR3 gene is prevalent in bladder cancers and may hold value as a prognostic marker and as a tool for patient selection." (PMID 33224141, 2020). "Bladder cancer patients with FGFR3 mutations have been associated with lower immune cell infiltration and lower TGFβ signals than patients without FGFR3 mutations." (PMID 32182655, 2020). "FGFR3 mutations are associated with less aggressive disease across all bladder cancers, although this is not necessarily the case among advanced tumors." (PMID 33224141, 2020). "Given the preponderance of FGFR3 alterations in bladder cancer, FGFR3 inhibitors in biomarker-selected patients using a urine biopsy might be a highly desirable path forward." (PMID 31803629, 2019). "Notably, ETV5 was one of the genes significantly downregulated after FGFR3 silencing in the bladder cancer cell line RT11251, or after treatment of cancer cell lines with the FGFR inhibitor AZD454752, independently confirming our results." (PMID 30952872, 2019). "Therefore, ScFv against FGFR3 has been screened and applied to study antitumor activity in bladder cancer for a long time." (PMID 31535232, 2019). "Our data show that ETV5 is important in maintaining the malignant phenotype of bladder cancer cells, and that its knockdown can recapitulate some of the phenotypic effects of FGFR3 knockdown in UC cells, such as decreased cell proliferation and reduced anchorage independent growth." (PMID 30952872, 2019). "FGFR3 plays an important role in the development of bladder cancer (BCa)." (PMID 30999937, 2019). "As examples of genetic biomarkers for bladder cancer, mutations in the fibroblast growth factor receptor 3 (FGFR3) oncogene are frequent in low-grade non-muscle invasive bladder cancer (NMIBC) tumors." (PMID 30769831, 2019). "In addition to bladder cancer, FGFR3 translocations and amplification of the CCND1 and MYC genes are common in multiple myeloma." (PMID 29423038, 2018). "In addition to FGFR3, alterations in a number of other genes including MYC and CCND1 (encoding cyclin D1), are found in bladder cancers and thought to contribute to oncogenesis." (PMID 29423038, 2018). "A phase I trial using an intermittent dosing schedule of the pan‐FGFR3 inhibitor JNJ‐42756493 on patients with advanced bladder cancer with confirmed FGFR alterations 28 and a case report for phase I AZD4547, a selective FGFR inhibitor targeting FGFR1/2/3 29, also showed promising results." (PMID 30043421, 2018). "The signaling pathway activated by mutated FGFR3 and FGFR3‐fusion proteins is not well characterized, particularly for bladder cancer." (PMID 29463565, 2018). "In addition, FGFR3 was upregulated in approximately 40% of invasive bladder tumors; this observation also implied that FGFR3 played an oncogenic role in bladder carcinoma." (PMID 29850625, 2018).
bladder cancer (continued). "This is not the case in bladder cancer since the majority of FGFR3‐mutated tumors are low‐stage, low‐grade tumors." (PMID 29463565, 2018). "The FGFR3/MYC positive feedback loop involving p38 and AKT activation by FGFR3 identified in bladder cancer cell lines may, therefore, also occur in human bladder tumors with genetic alterations of FGFR3." (PMID 29463565, 2018). "Interestingly, one functional study indeed proved that miR-99a inhibits cell proliferation, colony formation ability, migration and invasion by targeting fibroblast growth factor receptor 3 (FGFR3) in prostate cancer and bladder cancer." (PMID 29579063, 2018). "We demonstrate that bladder tumors not enriched for APOBEC mutagenesis frequently harbor mutations in FGFR3 or the RAS family of oncogenes, and we also demonstrate that APOBEC3A is expressed at significantly higher levels in the basal subtype of bladder cancer, compared to other subtypes." (PMID 29435122, 2018). "The strongest negative correlation (rho = 0.83) was between FGFR1 and FGFR3 in bladder carcinoma." (PMID 29322935, 2017). "In addition to the molecule mechanism how FGFR3 contributes to the bladder cancer progression, we tried to explore the clinical value of FGFR3." (PMID 28320388, 2017). "Thus far we have discussed the use of FGFR inhibitors assuming that FGF/FGFR is the primary driver for oncogenesis in certain histologies or in certain molecular aberrations such as FGFR3 fusion in bladder cancer." (PMID 28030802, 2017). "The current study may provide some insights into the molecular mechanism of FGFR3 as a mediator in bladder cancer." (PMID 28320388, 2017). "In addition, we found that FGFR3 knockdown downregulated DAPK1 in bladder cancer cell line, and TREK1 is coregulated with DAPK1 and a low level expression of TREK1 was also correlated with poor survival in 3 independent bladder cancer patient cohorts." (PMID 28388658, 2017). "Further investigation showed that FGFR3 knockdown resulted in downregulation of DAPK1 in bladder cancer cell line, suggesting that FGFR3 may be an upstream factor of DAPK1." (PMID 28388658, 2017). "A body of studies evidenced that FGFR3 acts as an important oncogenic driver in bladder cancer." (PMID 28320388, 2017). "The results further confirmed that the genes in the PPI network may be responsible for the carcinogenesis of FGFR3 in bladder cancer." (PMID 28320388, 2017). "Our results suggest that in a background of low FGFR3 expression, its activating mutation may play a significant role in suppressing the expression of DAPK1 in bladder cancer." (PMID 28388658, 2017). "Moreover, it has been proved that bladder cancer cell proliferation in culture is inhibited when the activation of FGFR3 was blocked." (PMID 28320388, 2017). "Besides, we predicted the potential prognostic makers from the DEGs in the FGFR3-centered PPI network for bladder cancer combined with the data retrieved from the dataset GSE31684." (PMID 28320388, 2017). "Titration of DNA extracted from the bladder cancer cell lines MGH-U3 (FGFR3 mutant) and SW-780 (TERT promoter mutant) into wtDNA demonstrated that the percentage of mutant reads reliably reflected the percentage of mutant DNA down to levels below the 2.5% threshold used here." (PMID 26901314, 2016). "Conversely, HGF was able to rescue FGFR3 inhibition in bladder cancer cells." (PMID 27655711, 2016). "FGFR3 has been identified as a particularly rational target for bladder cancer therapy." (PMID 27029060, 2016).